CRB2 (crumbs cell polarity complex component 2)
Description:
Apical polarity protein that plays a central role during the epithelial-to-mesenchymal transition (EMT) at gastrulation, when newly specified mesodermal cells move inside the embryo (By similarity). Acts by promoting cell ingression, the process by which cells leave the epithelial epiblast and move inside the embryo to form a new tissue layer (By similarity). The anisotropic distribution of CRB2 and MYH10/myosin-IIB at cell edges define which cells will ingress: cells with high apical CRB2 are probably extruded from the epiblast by neighboring cells with high levels of apical MYH10/myosin-IIB (By similarity). Plays a role in the maintenance of retinal neuroepithelium organization, structural integrity, adhesion, photoreceptor polarity and retinal photoreceptor layer thickness (By similarity). May play a role in determining the length of cone photoreceptor outer segments and proliferation of late-born progenitor cells (By similarity). Also required for maintenance of the apical polarity complex during development of the cortex (By similarity). Inhibits gamma-secretase-dependent cleavage of APP and secretion of amyloid-beta peptide 40 and amyloid-beta peptide 42, and thereby inhibits gamma-secretase-dependent Notch transcription.
Synonyms: FLJ38464; FLJ16786; FSGS9; VMCKD
Tractability: Small molecule: a structure with a bound ligand is known. Antibody: UniProt places it where antibodies can reach, with medium confidence; UniProt predicts a signal peptide or a membrane-spanning region; its Gene Ontology location is reachable by antibodies, with medium confidence. PROTAC: its protein half-life has been measured.
Gene: Protein-coding gene on chromosome 9 (123,356,170 to 123,380,324, forward strand). Ensembl gene ENSG00000148204.
Subcellular location: Apical cell membrane (Isoform 1); Cytoplasm; Cell junction; Secreted (Isoform 2)
Gene Ontology:
Molecular function: aspartic-type endopeptidase inhibitor activity; protein binding; protein-containing complex binding; calcium ion binding
Biological process: negative regulation of endopeptidase activity; circulatory system development; establishment of cell polarity; establishment or maintenance of epithelial cell apical/basal polarity; heterophilic cell-cell adhesion; ingression involved in gastrulation with mouth forming second; maintenance of epithelial cell apical/basal polarity; mesoderm formation; notochord formation; photoreceptor cell maintenance; positive regulation of BMP signaling pathway; positive regulation of epithelial to mesenchymal transition; regulation of gastrulation; retina homeostasis; retinal cone cell development; somitogenesis
Cellular component: extracellular exosome; protein-containing complex; anchoring junction; apical junction complex; apical plasma membrane; cytoplasm; plasma membrane; apical part of cell; apicolateral plasma membrane; cell junction; extracellular region; subapical complex
Genetic constraint (gnomAD): Loss-of-function variants: 83 observed, 82.88 expected, observed/expected ratio (o/e) 1, 90% interval 0.84 to 1.2. The synonymous counts are far from expectation, so gnomAD's model fits this gene poorly and the ratio says little. Missense variants: 1,841 observed, 1,614.6 expected, observed/expected ratio (o/e) 1.14, 90% interval 1.1 to 1.18. Synonymous variants: 907 observed, 726.54 expected, observed/expected ratio (o/e) 1.25, 90% interval 1.18 to 1.32.
Gene-disease validity (ClinGen):
ClinGen rates the evidence that CRB2 causes each of these diseases.
focal segmental glomerulosclerosis 9 (autosomal recessive): Definitive. Any focal segmental glomerulosclerosis in which the cause of the disease is a mutation in the CRB2 gene.
Homologues: Orthologues: chimpanzee CRB2 (99% identical), macaque CRB2 (95% identical), pig CRB2 (84% identical), dog CRB2 (81% identical), mouse Crb2 (78% identical), guinea pig CRB2 (78% identical), rat Crb2 (76% identical), tropical clawed frog crb2 (43% identical), zebrafish crb2b (27% identical). Paralogues in human: SCARF2 (13% identical), SCARF1 (13% identical), CRB3 (3% identical).
Diseases named in the same sentence as CRB2 in open-access papers:
CRB2 is named in the same sentence as 42 diseases in open-access papers, as found by Europe PMC text mining. Sharing a sentence is not in itself a finding about the gene and the disease. The quoted sentences say what the papers report.
retinitis pigmentosa (10 papers, 2013 to 2023). Retinitis pigmentosa (RP) is an inherited retinal dystrophy leading to progressive loss of the photoreceptors and retinal pigment epithelium and resulting in blindness usually after several decades. "Variants of CRB2 have been associated with retinal aberrations and more recently a missense mutation of CRB2 has been found to cause retinitis pigmentosa." (PMID 31795518, 2019). "Knockout of Crb2 in mice results in embryonic lethality during late gastrulation, likely due to disrupted polarity of epiblast cells, and conditional knockout of Crb2 in the retina causes retinal degeneration defects similar to those observed in retinitis pigmentosa." (PMID 35247383, 2022). "Recently, a missense mutation of CRB2 (p.R1249G) has been reported to cause retinitis pigmentosa." (PMID 34262913, 2021). "Recently, we showed that conditional deletion of mouse Crb2 in the retina results in early retinal disorganization leading to severe and progressive retinal degeneration with concomitant visual loss that mimics retinitis pigmentosa due to mutations in the CRB1 gene." (PMID 24324803, 2013). "In this study, we present a novel Müller cell-specific Crb1KOCrb2LowMGC retinitis pigmentosa mouse model (complete loss of CRB1 and reduced levels of CRB2 specifically in Müller cells)." (PMID 33575434, 2021). "In contrast, Crb2 cKO mice display a severe phenotype with progressive loss of photoreceptors and retinal activity mimicking CRB1-related retinitis pigmentosa." (PMID 24339791, 2013). "As no genotype-phenotype correlation in CRB1 retinal dystrophies has been identified, additional down-regulation of CRB2 function in human CRB1-mutant retinas might range from CRB1-retinitis pigmentosa to CRB1-LCA." (PMID 24339791, 2013). "Human CRB2 that is the CRB1 preferable substitute, was targeted in AAV both to Müller glial and photoreceptors into the retinitis pigmentosa mouse model, which ameliorated the retinal function and structure." (PMID 33308271, 2020). "Reduced levels of CRB2 in MGCs and/or photoreceptors or retinal progenitors in mice lacking CRB1 result in a significant more severe retinitis pigmentosa or Leber congenital amaurosis retinal phenotype." (PMID 33808129, 2021).
retinal degeneration (9 papers, 2013 to 2024). Degeneration of the retina. "Also, Crb2 mutations result in a progressive retinal degeneration similar to RP, and Crb2-deficient mice show gliosis and microglial activation." (PMID 36225228, 2022). "Interestingly, multiple studies highlight CRB2 as a modifier for CRB1-linked retinal degenerations." (PMID 38570189, 2024). "Therefore, we cannot exclude the possibility that rat Crb1 or Crb2 proteins could alleviate the loss of endogenous rat Crb1 in models with slower onset of retinal degeneration." (PMID 33808129, 2021). "We previously showed that CRB2 can rescue retinas lacking CRB1 or CRB2 proteins from retinal degeneration in two fast-progression RP mouse models by increasing the levels of CRB2 into both MGCs and PRCs." (PMID 33575434, 2021). "Although zebrafish Crb2b proteins are expressed in adult PRCs, and human CRB1 and CRB2 and Drosophila crb protect against retinal degeneration, we did not observe any gross defects in the structure of the retina nor in the ultrastructure of PRCs in old crb2be40 fish." (PMID 31988089, 2020).
nephrotic syndrome (8 papers, 2021 to 2025). A collection of symptoms that include severe edema, proteinuria, and hypoalbuminemia; it is indicative of renal dysfunction. "CRB2 mutation was reported to be a cause of steroid‐resistant nephrotic syndrome, potentially as disease‐associated CRB2 variants predominantly remain at the ER." (PMID 40698593, 2025). "In fact, loss of function variants of CRB2 can lead to steroid-resistant nephrotic syndrome resembling the clinical spectrum of Nephrin mutations." (PMID 40003707, 2025). "For example, in mice, it has been reported that autoantibodies against CRB2, a slit-diaphragm-associated protein, cause podocyte injury, resulting in nephrotic syndrome." (PMID 40768127, 2025). "There are also reports of Crb2 mutations in patients with steroid-resistant nephrotic syndrome, although the precise mechanism is unclear." (PMID 34654837, 2021). "For instance, KANK1 and CRB2, initially identified by our lab in one and four families respectively, have now been reported in seven and thirty-one families in Human Gene Mutation Database, indicating the evolving landscape of genetic discoveries in nephrotic syndrome." (PMID 38659911, 2024). "CRB2 variations were first identified in patients with isolated steroid resistant nephrotic syndrome and in patients with congenital nephrosis with cerebral ventriculomegaly." (PMID 36803301, 2023). "Notably, in humans, mutations in Crb2 result in filtration defects and nephrotic syndrome and wild-type Crb2 but none of these patient mutations can compensate for downregulation of Drosophila Crb in nephrocytes." (PMID 33651172, 2021).
retinal dystrophies (8 papers, 2013 to 2025). "Mutations in CRB1 and CRB2 are implicated in retinal dystrophies in humans and deletion of the Crb2 gene in the mouse retina was reported to perturb development of the photoreceptor layer defects." (PMID 34262913, 2021). "Mutations in the human CRB1 or CRB2 gene may lead to a broad spectrum of retinal dystrophies." (PMID 38802833, 2024). "In view of the association of renal anomalies, hydrocephalus/ventriculomegaly and retinal dystrophy, CRB2 has been proposed to lead to a phenotypic spectrum characteristic of a ciliopathy." (PMID 36803301, 2023). "Mouse CRB2 acts as the modifying factor of CRB1-related retinal dystrophies, since reduction or full ablation of CRB2 in combination with loss of CRB1 results in an exacerbation of the retinal phenotype observed in Crb1 knockout retinas." (PMID 31438467, 2019). "These preclinical studies provide preliminary evidence that CRB2 gene therapy might have the potential to improve retinal function and morphology in CRB1-associated retinal dystrophy." (PMID 40590804, 2025). "Loss of either CRB1 or CRB2 in MGCs results in mild retinal dystrophy, without impairing retinal function." (PMID 31438467, 2019). "Several polymorphisms in highly conserved residues have been identified in the CRB2 gene but not directly linked to retinal dystrophies." (PMID 24339791, 2013). "There was no additional pathogenic variant in any of the 230 retinal dystrophy genes analyzed on this NGS panel, which included the CRB2 gene." (PMID 34884448, 2021). "Crb1KOCrb2ΔimmPRC retinas lacking CRB1 and CRB2 from immature photoreceptors showed retinal dystrophy by fusion of the inner and outer nuclear layer throughout the retina." (PMID 31438467, 2019).
Leber congenital amaurosis (6 papers, 2013 to 2021). Leber congenital amaurosis (LCA) is a retinal dystrophy defined by blindness and responses to electrophysiological stimulation (Ganzfeld electroretinogram (ERG)) below threshold, associated with severe visual impairment within the first year of life. "Here, we report that ablation of Crb1 and Crb2 genes results in severe impairment of retinal function, abnormal lamination and thickening of the retina mimicking human Leber congenital amaurosis due to loss of CRB1 function." (PMID 24339791, 2013). "Among these are retinitis pigmentosa 12 (RP12) and Leber congenital amaurosis (LCA), severe ocular dystrophies leading to PRC degeneration caused by mutations in CRUMBS1 (CRB1) or CRB2." (PMID 31988089, 2020). "While mutations in human CRB1 are associated with early-onset retinitis pigmentosa (RP12) and Leber congenital amaurosis (LCA), it seems to be Crb2 in the mouse that has taken on this function." (PMID 28202468, 2017).
Ventriculomegaly (4 papers, 2019 to 2025). An increase in size of the ventricular system of the brain. "CRB2 mutations are linked to focal segmental glomerulosclerosis and ventriculomegaly with cystic kidney disease, but their full phenotypic spectrum remains unclear." (PMID 40456931, 2025).
retinal disease (3 papers, 2013 to 2023). "One of the main working hypothesis that we draw from our four CRB1-LCA-like models is that CRB2 protein levels may be lower or that a less functional variant is of CRB2 is expressed in CRB1 LCA patients compared to less severe CRB1 retinal diseases." (PMID 31795518, 2019). "Therefore, missense variants of CRB2 in humans are likely to have small but important effects on retinal diseases." (PMID 31795518, 2019). "This phenotype with outer retinal abnormalities is similar to CRB1 patient-derived retinal organoids and Crb1 or Crb2 mutant mouse retinal disease models." (PMID 37886604, 2023). "From Crb2 cKO, Crb1+/−Crb2 cKO and Crb1Crb2 cKO retina studies, the severity of the retinal disease is inversely proportional to the amount of CRB1 and CRB2 proteins which seemed to be critical for the development of the retina." (PMID 24339791, 2013).
Blindness (2 papers, 2017). Blindness is the condition of lacking visual perception defined as a profound reduction in visual perception. "Interestingly, mutations in human CRB1 result in RP12-asssociated blindness, despite the fact that CRB2 and CRB3 are also expressed in the retina." (PMID 28202468, 2017).
ciliopathy (2 papers, 2023 to 2024). A genetic disorder of the cellular cilia or the cilia anchoring structures, the basal bodies, or of ciliary function. "CRB2-linked pathology has been debated as a ciliopathy-like syndrome as the pathological defects are comparable to those described in ciliopathy patients." (PMID 38570189, 2024).
congenital nephrosis (2 papers, 2022 to 2023). "On the apical side, variants in CRB2, a key Crumbs complex member, have been linked to SRNS and congenital nephrosis, Finnish type." (PMID 35265622, 2022).
Congenital nephrotic syndrome (2 papers, 2018 to 2025). "Congenital nephrotic syndrome (CNS) is a rare disorder caused by mutations in genes essential for podocyte function and glomerular slit diaphragm integrity, including CRB2 (Crumbs Cell Polarity Complex Component 2)." (PMID 40456931, 2025). "The evidence that gene mutations in the polarity determinant Crumbs homologs-2 (CRB2) cause congenital nephrotic syndrome suggests the functional importance of this gene product in podocyte development." (PMID 30125302, 2018).
focal segmental glomerulosclerosis (2 papers, 2021 to 2025). A renal disorder characterized by sclerotic lesions in the glomeruli. "Overall, this study's results suggest that the specific deprivation of Crb2 in podocytes causes alteration of the actin cytoskeleton, dysfunction, and accelerated apoptosis of podocytes leading ultimately to focal segmental glomerulosclerosis." (PMID 34654837, 2021). "Overall, this study's results suggest that the specific deprivation of Crb2 in podocytes induces altered actin cytoskeleton reorganization associated with dysfunction and accelerated apoptosis of podocytes that ultimately cause focal segmental glomerulosclerosis." (PMID 34654837, 2021). "Based on these observations, we speculate that loss-of-function of CRB2 in podocytes induces abnormal reorganization of the actin cytoskeleton and major susceptibility to apoptosis, leading to increased loss of podocytes and ultimately to focal segmental glomerulosclerosis." (PMID 34654837, 2021). "The present study demonstrated that podocyte-specific Crb2 knockout mice develop massive albuminuria and microhematuria 2-month after birth and focal segmental glomerulosclerosis and tubulointerstitial fibrosis with hemosiderin-laden macrophages at 6-month of age." (PMID 34654837, 2021).
glomerulopathy (2 papers, 2020 to 2025). "Biallelic pathogenic variants in CRB2 result in a glomerulopathy with additional systemic features in a minority of cases." (PMID 32467597, 2020). "The genes with the highest lifetime risk for monogenic glomerulopathy were COL4A3, followed by COL4A4, CRB2, NPHS1, and NPHS2." (PMID 40677321, 2025).
Hydrocephalus (2 papers, 2019 to 2023). Hydrocephalus is an active distension of the ventricular system of the brain resulting from inadequate passage of CSF from its point of production within the cerebral ventricles to its point of absorption into the systemic circulation. "Our study thus highlights that hydrocephalus related to CRB2, MPDZ and CCDC88C constitutes a separate pathogenic group of congenital non-communicating hydrocephalus with atresia of both Sylvius aqueduct and central canal of the medulla." (PMID 36803301, 2023). "To date, 34 cases with CRB2 bi-allelic variations have been reported, including many cases with hydrocephalus, but, partly because this gene was first considered as causal for renal abnormalities, no neuropathological characterization has been performed until now." (PMID 36803301, 2023). "Neurohistopathological analysis allowed us to demonstrate that, contrary to what was previously proposed, the pathological mechanisms underlying hydrocephalus secondary to CRB2 variations are not due to stenosis but to atresia of both Sylvius Aqueduct and central medullar canal." (PMID 36803301, 2023). "At stage 45, most of the crb2 F0 CRISPR mutant tadpoles had aqueductal obstruction but no obvious hydrocephalus." (PMID 30996265, 2019).
kidney failure (2 papers, 2023 to 2025). An acute or chronic condition that is characterized by the inability of the kidneys to adequately filter the blood. "This case expands the phenotypic spectrum of CRB2-associated disease, demonstrating survival beyond infancy, progression to kidney failure, and highly complex transplant outcomes." (PMID 40456931, 2025). "Despite these findings, there is still a considerable gap in understanding the clinical trajectory of CRB2-associated CNS beyond infancy, especially regarding progression to kidney failure or outcomes following kidney transplantation." (PMID 40456931, 2025). "Vice versa, even the WT reference version of CRB2 is not completely exported to the cell surface, indicating that the ER-to-PM transport of SD proteins is a highly dynamic process and renal failure linked to the CRB2 gene is most probably caused by podocytes that fail to transport CRB2 to the SD." (PMID 36549870, 2023). "Subsequent case reports described several children with CRB2 mutations who developed SRNS without progression to kidney failure, highlighting the heterogeneity of CRB2-related phenotypes." (PMID 40456931, 2025).
cardiomyopathy (1 paper, 2025). A disease of the heart muscle or myocardium proper. "The additional features of cardiomyopathy, ventriculomegaly, and neuronal migration defects further illustrate the broad spectrum of manifestations linked to CRB2 mutations." (PMID 40456931, 2025).
cystic kidney disease (1 paper, 2025). A congenital or acquired kidney disorder characterized by the presence of renal cysts. "Mutations in CRB2 have been linked to focal segmental glomerulosclerosis type 9 (FSGS9) and ventriculomegaly with cystic kidney disease." (PMID 40456931, 2025).
Epithelial Ovarian Cancer (1 paper, 2026). "Functional assays revealed that CRB2 enhances ovarian cancer cell proliferation, migration, and invasion, while suppressing apoptosis." (PMID 41906249, 2026). "CRB2 may serve as a novel prognostic biomarker and therapeutic target for epithelial ovarian cancer." (PMID 41906249, 2026).
intellectual deficiency (1 paper, 2023). "In addition, specific ablation of Crb2 in the mouse telencephalon leads to cortical lamination abnormalities that are transient, indicating that early transient anomalies cannot be excluded in patients with CRB2 variations that might partially underlie intellectual deficiency and seizures." (PMID 36803301, 2023).